BRAF (B-Raf proto-oncogene, serine/threonine kinase)
Diseases named in the same sentence as BRAF in open-access papers (continued):
Sharing a sentence is not in itself a finding about the gene and the disease.
melanoma (continued). "Regarding BRAF-mutated cases, superficial spreading melanoma (SSM) was the most frequent subtype (11/24, 46%)." (PMID 39000050, 2024). "MAPKP inhibitors, particularly BRAF inhibitors like vemurafenib, are associated with the development of cSCCs and second primary melanomas (SPMs)." (PMID 38893081, 2024). "Predictive markers, like the BRAF mutation status in melanoma, help determine the likelihood of a patient’s response to specific treatments, such as BRAF/MEK inhibitors." (PMID 39273605, 2024). "Conclusions on the efficacy of this treatment are to follow, as this treatment can prove promising for stage II BRAF mutated melanoma." (PMID 38891988, 2024). "Remarkably, NOX4 inhibitors have shown promises as adjuncts to current therapies, particularly for melanoma patients with BRAF mutations." (PMID 38982044, 2024). "Multiple BRAF-targeted therapies (i.e., vemurafenib, dabrafenib, and encorafenib) have been designed to specifically treat melanomas of this genotype by limiting the mutation’s ability to affect downstream MAP kinase signaling." (PMID 38473384, 2024). "In our cohort, most patients with BRAF-mutated melanoma opted for combination therapy with BRAF plus MEK inhibitors." (PMID 39123482, 2024). "Melanomas on skin intermittently exposed to sun frequently carry somatic BRAF mutations and have a higher nevus count, while melanomas chronically exposed to solar UVR have a low nevus count and NRAS and KIT mutations." (PMID 38927967, 2024). "The BRAF gene is associated with cell proliferation and growth, and approximately 40% to 60% of melanoma patients have BRAF V600 mutations." (PMID 39682248, 2024). "BRAF with V600E mutation is constitutively active and BRAF has been shown to be one of the important driver genes of melanoma." (PMID 38087810, 2024). "We evaluated OS and PFS for patients with BRAF mutations from the ICI cohort (Miao_Melanoma-OS and Miao_Melanoma-PFS datasets) to generate survival curves using Kaplan–Meier analysis." (PMID 39195270, 2024). "In melanoma, for instance, where mutations in BRAF are prevalent in 40–50% of cases, extensive studies to inhibit mutated BRAF using drugs like vemurafenib and dabrafenib have been conducted in clinical setting." (PMID 38424542, 2024). "In fact, NF1 loss-of-function mutations frequently co-occur with BRAF non-V600 class II mutations; in fact, melanomas harboring BRAF III non-V600 mutations have frequently co-occurring NF1 loss-of-function mutations (67%) and RAS mutations (22%)." (PMID 39727691, 2024). "Approximately 40–60% of melanomas harbor mutations in the BRAF gene, with the V600(E/K) mutation being the most common." (PMID 39684531, 2024). "At the molecular level, it is supposed that somatic mutations in NRAS and BRAF, which occur mutually exclusive, are critical in this multistep development of melanoma." (PMID 38396984, 2024). "Two randomized studies (SECOMBIT, DREAM-SEQ) analyzing treatment sequences in advanced BRAF-mutated melanoma have recently published their data." (PMID 38450188, 2024). "Studies in patients with advanced melanoma carrying a BRAFV600E mutation have shown that combining BRAF and MEK inhibitors resulted in a higher rate of complete/partial responses and median progression-free survival compared with monotherapy groups." (PMID 37985676, 2024). "Several clinical trials have evaluated this combinational treatment strategy in patients with advanced melanoma characterized by BRAF mutations." (PMID 39086722, 2024). "With this review, we set out to clarify the type, incidence and relative risk of adverse oral events in patients with melanoma who are being treated with a combination of BRAF and MEK inhibitors." (PMID 38201012, 2024). "One of the most recurrent genetic alterations observed in melanoma is mutations of the BRAF protein kinase, whose constitutive activation plays a key role in the early stages of development of melanomas." (PMID 39727691, 2024).
melanoma (continued). "Experiments have demonstrated that in melanoma caused by BRAF mutations, the induction of cellular senescence by the BRAFi vemurafenib leads to the resistance of melanoma cells to this inhibitor." (PMID 39161800, 2024). "Vemurafenib was the first BRAF inhibitor to be approved and is indicated in melanomas with BRAF V600E mutations." (PMID 38345654, 2024). "The study cohort comprised 31 patients (30%) with melanoma harboring the BRAF V600E/K mutation, treatable with BRAF/MEK inhibitors." (PMID 39564955, 2024). "The BRAF V600D/R subtype had the highest prevalence in patients with scalp-arising melanoma (3.8% vs. 1.5%), reflecting a greater association with hairy skin." (PMID 39735251, 2024). "Specifically, type I DN share frequent BRAF V600E mutations, a younger age, a more nested growth pattern, and a lower degree of solar elastosis with melanomas on skin with low cumulative sun damage (CSD)." (PMID 38371417, 2024). "To test this prediction, we assessed RAF-induced MAPK pathway activation in SK-MEL-2 melanoma cells expressing wild-type BRAF and a gain-of-function variant of N-RAS (Q61R)." (PMID 38742856, 2024). "Age plays an important role in the occurrence and presence of BRAF mutations in patients with melanoma." (PMID 39200941, 2024). "BRAF mutations are detected in ~7%–15% of all cancers, including hairy cell leukemia (79%–100%), melanomas (40%–70%), papillary thyroid cancers (45%), ovarian cancers (35%), and multiple myeloma (4%)." (PMID 38560563, 2024). "Examples of basket trials include a study of imatinib in multiple histological subtypes of advanced sarcoma, a study of vemurafenib in BRAF V600 mutation-positive non-melanoma cancers, and a study of larotrectinib in TRK fusion-positive cancers, among others." (PMID 38254740, 2024). "From this point of view, the identification of BRAF mutation in melanoma, in 2002, has opened up a new perspective in deciphering the carcinogenic mechanism and has provided the molecular basis for the development of new classes of therapeutic agents." (PMID 38541077, 2024). "For instance, the tumor driving BRAF(V600E) mutation, which is present in approximately 50% of human melanomas, suppresses mitochondrial oxidative phosphorylation and drives aerobic glycolysis through the activation of hypoxia inducible factor 1 subunit alpha." (PMID 38474307, 2024). "Mutations in BRAF can be found in about 50% of melanomas and are mainly associated with cell proliferation." (PMID 38790974, 2024). "The BRAF (V600E) mutation is common in malignant melanoma patients and drives constitutive activation of the MEK/ERK signaling pathway and cancer progression." (PMID 39070550, 2024). "Several studies linked BRAF mutation with an unfavorable prognosis, its presence being associated with a reduced survival in stage IV melanoma, compared to patients showing the wild type." (PMID 38541077, 2024). "Melanomas with ≥ 10 CNMs more frequently show ulceration (p < 0.02) and the BRAF V600E mutation (p < 0.02)." (PMID 39099686, 2024). "For example, vemurafenib (BRAF inhibitor) inhibits melanoma through targeting mutated BRAF, whereas pembrolizumab (anti–PD-1 antibody) blocks the immune checkpoint PD-1 on T cells to increase antitumor immunity." (PMID 38334978, 2024). "Brain metastases are particularly common for patients with melanoma, which is one of the major histologies in which BRAF mutations are found." (PMID 38539548, 2024). "For advanced melanoma, current treatment strategies primarily include ICIs and, for patients with BRAF mutations, combination therapies of BRAF and MEK inhibitors." (PMID 39669853, 2024). "While RAF-targeted therapy has shown remarkable efficacy in treating melanoma patients with BRAF mutations, several critical gaps and challenges persist in its clinical application." (PMID 39582535, 2024).
melanoma (continued). "This type of melanoma rarely presents mutations in the BRAF and NRAS genes, common in other melanomas, but has a high frequency of mutations in the KIT gene, which can activate the MAPK signaling pathway." (PMID 39202970, 2024). "On the other hand, selective BRAF inhibitors (BRAFi) have demonstrated remarkable clinical activity in melanoma patients carrying BRAFV600 mutations, which improved with the combination with MEK inhibitors (MEKi)." (PMID 39273452, 2024). "A total of 42% had BRAFnon-V600K melanoma, 14% had BRAF V600K tumors, 18% had NRAS mutations, and 26% were wild-type for both BRAF and NRAS." (PMID 38339344, 2024). "In melanoma, the BRAF gene is the most commonly mutated, with the BRAF subtype detected in approximately 50% (40% to 60%) of individuals, activating the mitogen-activated protein (MAP) kinase pathway." (PMID 38891988, 2024). "The effects observed with trametinib in combination with CQ were not limited to pancreatic cancer; patient-derived xenografts (PDX) of other tumors, including NRAS-mutated melanoma and BRAF-mutated colorectal cancer, showed similar responses." (PMID 39272847, 2024). "The BRAF mutation was detected in 40% of the 25 patients who had already been diagnosed with melanoma." (PMID 39200941, 2024). "In this study, we examined how the downregulation and overexpression of RIPK4 affect the sensitivity of BRAF-mutated melanoma cells (A375 and WM266.4) to CisPt and DOX along with determining the underlying mechanism." (PMID 39766280, 2024). "Altogether, ASO-mediated T-RECS inhibition represents an unprecedented therapeutic opportunity to treat NRAS-/BRAF-mutated melanoma." (PMID 38383439, 2024). "In melanoma, immunotherapy targeting the BRAF(V600E) mutation represents a promising treatment option, especially for melanoma patients with traditional drug resistance." (PMID 39052013, 2024). "Factors such as melanoma subtype, lymphocyte count, and BRAF mutation status were identified as key influencers of treatment efficacy." (PMID 39234260, 2024). "Activating BRAF mutations have been reported in more than 50% of melanomas, 90% of which have the V600E mutation." (PMID 38965534, 2024). "For this purpose, we employed the (i) MEK inhibitor trametinib and (ii) vemurafenib plus cobimetinib, an FDA- and EMA-approved BRAF/MEK inhibitor combination for BRAFV600-mutated melanoma." (PMID 39835134, 2024). "The most common mutation in BRAF in melanoma (found in over 90% of cases) is a substitution of valine with glutamic acid at position 600 (V600E)." (PMID 38519031, 2024). "For instance, nearly 50% of UV exposure-related melanomas contain BRAF mutations, with p.V600E (i.e., a valine to glutamic acid substitution) being the most common (>90% of all BRAF mutations)." (PMID 38790156, 2024). "We demonstrated that ACA-28 has a unique property to induce ERK-dependent apoptosis in melanoma cell lines (with either BRAF or NRAS mutation) as well as NIH/3T3 cells harboring mutationally active HER2/ErbB2." (PMID 38500550, 2024). "Dabrafenib has been approved by the Food and Drug Administration (FDA) for the treatment of BRAF mutated (V600E) advanced melanoma, and recently approved in combination with trametinib for BRAF mutated advanced solid tumors." (PMID 39596471, 2024). "Trametinib is a selective MEK1 and MEK2 inhibitor, and it has evolved as a pivotal therapeutic agent targeting the MAPK/ERK pathway in various malignancies, including BRAF-mutated melanoma, non-small cell lung cancer and thyroid cancer." (PMID 38473413, 2024). "Due to the association of BRAF mutations with melanoma and lung cancer, he was subsequently referred to a respiratory physician to screen for a possible lung primary and dermatologist to screen for melanoma." (PMID 39516362, 2024).
melanoma (continued). "Trametinib, a mitogen-activated protein kinase (MAPK) inhibitor, is primarily utilized in the therapeutic management of melanoma characterized by BRAF V600E or V600K mutations." (PMID 39707474, 2024). "In this study, we demonstrated that CTHRC1 was positively correlated with the BRAF(V600E) mutation in human colon cancer, thyroid cancer, and melanoma." (PMID 39052013, 2024). "BRAF mutations: For melanomas with BRAF mutations, BRAF inhibitors like vemurafenib and dabrafenib, combined with MEK inhibitors like trametinib, have demonstrated significant survival benefits." (PMID 39859956, 2024). "The most prevalent class I BRAFV600 mutation (35–50% of melanomas) gives rise to a constantly active monomer BRAF kinase, generating high levels of active phosphorylated ERK (p-ERK)." (PMID 39682270, 2024). "A study of whole-genome sequences from cutaneous, acral, and mucosal subtypes of melanoma in 183 melanoma samples found that BRAF, NRAS, and NF1 were significantly mutated genes in AM, while SF3B1 (splicing factor 3B subunit 1) was identified in MM." (PMID 38469235, 2024). "BRAF mutations, particularly V600E, occur in approximately 40% of melanoma cases and 80% of melanocytic nevi, but alone are insufficient for disease initiation, indicating the potential involvement of additional genetic or environmental factors." (PMID 39519202, 2024). "While targeted inhibition of BRAF and MEK has resulted in improved survival in patients with BRAF V600E-mutated melanoma, therapeutic resistance is often the end result." (PMID 38247727, 2024). "In patients with BRAF-mutated melanoma, the downstream pro-survival mitogen-activated protein kinase (MAPK) pathway is consistently activated, leading to elevated tumor growth and progression." (PMID 38338893, 2024). "ERK activation is driven by YES1, suggesting a potential mechanism that contributes to drug resistance in patients with melanoma and BRAF mutations who undergo combined BRAF and MEK inhibition." (PMID 38338729, 2024). "This approach was recently examined in the DREAMseq Trial, revealing a superiority on the overall survival (OS) of primary immunotherapy over primary targeted therapy in BRAF-mutated progressive melanoma patients." (PMID 39125519, 2024). "Patients with advanced melanoma can be categorized into two groups based on their BRAF mutations: V600 and non-V600." (PMID 39582535, 2024). "The cell lines were representative of the three most common mutations detected in melanoma: A375 harbors a mutation for BRAF, Mel224 a mutation for NRAS, and the CHL-1 line is wild type for these two genes." (PMID 38892279, 2024). "One of the prominent mutational drivers in melanoma is the BRAF gene, specifically the BRAF V600 mutation." (PMID 39234260, 2024). "BRAF mutations are usually identified in the codon 600 of the BRAF gene and are reported in 40–60% of melanoma cases." (PMID 38396984, 2024). "The aim was to identify early‐stage melanoma patients at high risk of recurrence using liquid biopsy, estimating of mutated BRAF ctDNA and the level of tumor marker S100B in plasma." (PMID 39387479, 2024). "In melanoma cells, mutations in the BRAF gene and anomalies in signaling pathways involving PI3K, AKT, and RAS favor the constitutive activity of NF-κB, resulting in enhanced proliferation and apoptosis resistance." (PMID 39519202, 2024). "In the 23 cases of BRAF mutated melanoma samples, we found a mean allele frequency of 42 percent (range 6–84%)." (PMID 39125519, 2024). "Approximately 60% of melanoma patients present somatic mutations of BRAF, a proto-oncogene that encodes a serine/threonine kinase crucial for the MAPK signaling pathway." (PMID 39086722, 2024). "Melanoma patients with BRAF mutations also showed a significantly higher PScore than patients without BRAF mutations." (PMID 38229080, 2024).
melanoma (continued). "Similar results were found here with regard to advanced melanoma patients who progressed to BrM, as patients with BRAF mutation had a higher proportion of BrM development than those without a mutation." (PMID 38730723, 2024). "BRAF mutations are frequently detected in melanoma and were identified in arrays of cancers including colorectal cancer, non–small cell lung carcinoma, non–Hodgkin lymphoma, hairy cell leukemia, and thyroid cancer." (PMID 38919805, 2024). "Conversely, malignant melanoma arises from melanocytes, pigment-producing cells scattered throughout the epidermis, dermis, and mucous membranes, where mutations in genes, such as BRAF and NRAS, drive melanocyte transformation and metastasis." (PMID 38674007, 2024). "This combination represents the current standard of care for BRAF-mutated melanoma in adjuvant or definitive treatment settings." (PMID 39165562, 2024). "Targeted therapies and immunotherapy are currently considered the mainstay first-line treatment for advanced BRAF-mutated melanoma." (PMID 38450188, 2024). "Molecular therapies have completely changed the treatment landscape and prognosis for malignancies driven by specific mutations, such as BRAF V600E, in melanoma." (PMID 39325541, 2024). "A combination of RAF, MEK, and ERK inhibitors effectively suppressed tumor growth in xenograft models derived from samples of both targeted therapy-naive and pre-treated patients with melanoma or lung cancer and BRAF V600E mutations." (PMID 39684685, 2024). "There are single-gene tests, like the ones that check for EGFR mutations in non-small cell lung cancer, or BRAF mutations in melanoma." (PMID 39199313, 2024). "Nuclear localization of BRAF V600E in melanoma cells has been shown to be associated with aggressive biological behavior and BRAF inhibitor resistance." (PMID 39272837, 2024). "The BRAF-targeted therapy or combined with immunotherapy is recommended for patients with BRAF-mutated melanoma." (PMID 39530091, 2024). "Melanoma cells that harbor this mutation exhibit low levels of activated RAS that are less likely to mediate BRAF V600E dimerization and direct downstream signaling." (PMID 38672652, 2024). "We found distinct roles for pyroptosis in primary and metastatic melanoma patients, with a certain association between pyroptosis and BRAF mutation status, revealing a potential combination strategy of drug usage in melanoma." (PMID 38229080, 2024). "In contrast, type II DN are similar to high-CSD melanomas in that they lack BRAF V600E mutations, affect older individuals, have more solar elastosis, and have a lentiginous growth pattern." (PMID 38371417, 2024). "We reasoned that the different ways in which panRAF and MEK inhibitors combine in NRAS vs. BRAF mutant melanomas likely originate from the distinct pathway rewiring caused by these oncogenic mutations." (PMID 39199684, 2024). "In melanoma, BRAF inhibitors can sensitize melanoma cells to agents that cause ferroptosis, which reduces the abundance of SLC7A11 transcripts." (PMID 38336727, 2024). "Introduced in 2008, Vemurafenib is a selective inhibitor of the oncogenic kinase B-Raf, targeting melanoma with the BRAF V600E mutation." (PMID 39199653, 2024). "Trametinib, which specifically targets MEK1 and MEK2, has been approved to treat metastatic or unresectable melanoma with BRAF V600E or V600K mutations and as adjuvant therapy." (PMID 38474231, 2024). "Further studies are necessary to better evaluate the impact of NRAS and BRAF mutations on the response to ipilimumab in melanoma and to define the best treatment for these patients after iPD1 therapy failure." (PMID 39410017, 2024). "Melanomas fall into 4 genomic categories based on driver mutations: BRAF (50%), NRAS (25%), or NF1 (15%) mutant and triple WT." (PMID 38319712, 2024). "NRAS mutations are typically mutually exclusive of BRAF mutations, reinforcing their unique role in melanoma’s molecular pathology." (PMID 38474231, 2024).